STC2 (stanniocalcin 2)
Diseases named in the same sentence as STC2 in open-access papers (continued):
Sharing a sentence is not in itself a finding about the gene and the disease.
atherosclerosis (4 papers, 2018 to 2024). A disease characterized by the build-up of fatty material and calcium deposition in the arterial wall resulting in partial or complete occlusion of the arterial lumen. "Subsequent pre-clinical studies have established proof-of-principle for inhibiting the proteolytic activity of PAPP-A in atherosclerosis either using recombinant STC2 or an antibody specifically targeting the LNR domain of PAPP-A30." (PMID 39308741, 2024). "Stanniocalcin 2 (STC2), a secreted glycoprotein hormone, regulates many biological processes, including cell proliferation, apoptosis, tumorigenesis, and atherosclerosis." (PMID 30038584, 2018). "Stanniocalcin 2 (STC2), which is a glycoprotein hormone, regulates a series of biological processes in an autocrine or paracrine manner, such as cell proliferation, tumorigenesis and atherosclerosis." (PMID 32759741, 2020). "Our findings support the hypothesis that the Stanniocalcin-2/PAPP-A/IGFBP-4 axis is of remarkable importance in the vascular response to injury and in atherosclerosis and plays an important role in the risk stratification of STEMI patients." (PMID 29712555, 2018).
breast tumor (4 papers, 2011 to 2015). "STC2 was expressed in invasive breast tumor cells, while univariate survival analysis revealed that expressions of STC2 were correlated with longer disease-free survival." (PMID 23548070, 2013). "The expression of STC2 is induced in MCF-7 cells and the endometrial gland of women by 17β-estradiol and in breast tumors." (PMID 26512648, 2015). "The PR gene, PGR, and 3 other genes (GATA3, STC2 and GLI3) are increased in their expression, whereas the expression of 6 genes (AURKA, BUB1, CDC20, MKI67, HJURP, and CENPA) is decreased in PR-positive breast tumors." (PMID 22022496, 2011).
colon adenocarcinoma (4 papers, 2021 to 2023). "Our study on colon adenocarcinoma revealed that STC2 expression was also associated with CD4+ T and CD8+ T cells." (PMID 36685853, 2022).
head and neck cancer (4 papers, 2019 to 2026). A primary or metastatic malignant neoplasm affecting the head and neck. "Mutations in STC2 have a close relationship with the pathogenesis of head and neck cancer." (PMID 36685853, 2022).
Hyperglycemia (4 papers, 2018 to 2025). An increased concentration of glucose in the blood. "In this study, Ephx2, Stc2, Cep19, Il15 and Fbxw7 genes were found to be associated with impaired glucose tolerance and hyperglycemia." (PMID 32095365, 2020). "Thus, the significantly downregulated Stc2, Il15, and Fbxw7 might associate with hyperglycemia and impaired glucose tolerance in GK rats at 3 and 4 weeks of age." (PMID 32095365, 2020). "In addition, fasting hyperglycemia and insulin resistance were improved by STC2 overexpression in ob/ob mice." (PMID 30038584, 2018).
stomach adenocarcinoma (4 papers, 2022 to 2024). "Three of those, HENMT1, GRIN2A, and STC2, seem to relate to processes such as hypoxia response and hormone-metabolism regulation, thereby contributing to the development and progression of several carcinomas, including gastric adenocarcinomas." (PMID 38542354, 2024).
breast invasive carcinoma (3 papers, 2014 to 2025). "The STC2 is positively correlated with MSI including LIHC, LUSC, ovarian serous cystadenocarcinoma (OV), SARC, TGCT, THYM and negatively correlated with breast invasive carcinoma (BRCA), and COAD." (PMID 40535801, 2025).
Hepatic steatosis (3 papers, 2024 to 2025). Steatosis is a term used to denote lipid accumulation within hepatocytes. "The STC2 gene was reported to ameliorate hepatic steatosis by activating STAT3 signaling in mice." (PMID 38338026, 2024).
laryngeal carcinoma (3 papers, 2014 to 2022). Carcinoma that arises from the laryngeal epithelium. "STC2 is highly expressed in laryngeal cancer but not in normal tissues." (PMID 34612765, 2021).
skin cutaneous melanoma (3 papers, 2021 to 2022). "Conversely, STC2 expression levels were negatively correlated with TMB in BRCA (r = −0.34, p < 0.001), ESCA(r = 0.24, p < 0.01), KIRP (r = −0.12, p < 0.05), PAAD (r = −0.24, p < 0.01), skin cutaneous melanoma (SKCM) (r = −0.10, p < 0.05), and THCA (r = −0.12, p < 0.01)." (PMID 35937984, 2022).
Stroke (3 papers, 2022 to 2025). Sudden impairment of blood flow to a part of the brain due to occlusion or rupture of an artery to the brain. "Lentiviral transduction of NPCs with STC2 gain and loss of function demonstrates that STC2 is a critical mediator for enhanced functional recovery after stroke." (PMID 35292643, 2022). "But, it is plausible that these patients suffering from stroke exhibit a reduction in STC2 expression." (PMID 41155293, 2025). "Because Ca2+ entry into platelets is crucial for platelet aggregation, and we found downregulation of STC2 expression in the platelets from thrombotic patients, STC2 alteration may underlie thrombotic incidents in these subjects, particularly in thrombotic patients suffering from stroke/ictus." (PMID 41155293, 2025). "Altogether, our data allow us to conclude that STC2 represents a promising marker of stroke/ictus in thrombotic patients." (PMID 41155293, 2025). "To further investigate the effect of STC2 alone on stroke recovery, we intraventricularly administered recombinant STC2 1-week post-stroke." (PMID 35292643, 2022). "Administration of ASA for short time periods (less than a year of medication with 100 mg on a daily basis) did not statistically modify the STC2 expression values observed in the stroke/ictus patient group, despite reduced STC2 expression being found in comparison to other drugs." (PMID 41155293, 2025). "However, long-term administration of ASA of up to 10 years was able to reverse the reduction in the STC2 expression found in patients suffering from stroke (n = 5, p < 0.05)." (PMID 41155293, 2025). "Thus, our results from patients with stroke/ictus presented a clear reduction in STC2 expression in their platelets, finding less STC2 content in the youngest thrombotic patients." (PMID 41155293, 2025). "We found that administration of STC2 leads to an improvement in functional recovery and to an increase in endogenous neuroblasts migrating toward the peri-infarct region (BrdU, with Doublecortin at 6 weeks post-stroke)." (PMID 35292643, 2022). "Given STC2 plays a role in cell proliferation and survival, we found it an interesting candidate to further explore its role in stroke recovery and the increase in endogenous stem cell production seen with combined stem cell delivery and electrical stimulation." (PMID 35292643, 2022). "Moreover, direct administration of recombinant STC2 leads to an increase in migratory neuroblasts toward the penumbral region and an improvement in behavioral outcome in our rodent stroke model." (PMID 35292643, 2022). "Moreover, intraventricular administration of recombinant STC2 post-stroke confers functional benefits." (PMID 35292643, 2022). "Thus, STC2 appears to be an essential pathway for the increased production of endogenous stem cells in addition to functional recovery following stroke." (PMID 35292643, 2022). "Interestingly, VT may appear as a complication of previous stroke/ictus conditions and, thus, STC2 may represent a possible molecular tool to identify and differentiate the origin of both types of thrombotic events." (PMID 41155293, 2025). "With reduced NPC production of STC2, the benefit of the therapy in stimulated and unstimulated groups was diminished, suggesting that STC2 is an important pathway for stem cell effects on stroke recovery irrespective of its role in the improvement seen with electrical stimulation." (PMID 35292643, 2022).
endometrial carcinoma (2 papers, 2022). A malignant tumor arising from the epithelium that lines the cavity of the uterine body. "STC2 is identified as a screening marker for endometrial cancer in combination with CRELD1, GRK5 and SLC25A27." (PMID 35501821, 2022).
fibrosarcoma (2 papers, 2005 to 2022). A malignant mesenchymal fibroblastic neoplasm affecting the soft tissue and bone. "In accordance, STC2 is also detected in the culture medium of tumour cell lines derived from glioma and fibrosarcoma." (PMID 35501821, 2022). "Both STC1 and STC2 are reported to be secreted as phosphoproteins from human fibrosarcoma, a tumor of mesenchymal cells." (PMID 16343351, 2005). "Moreover, in human fibrosarcoma cells, STC2 has been reported to be phosphorylated between Serine-285 and Serine-298 in the C-terminal region by casein kinase." (PMID 35501821, 2022).
ischemia (2 papers, 2014 to 2025). A hypoperfusion of the BLOOD through an organ or tissue caused by a PATHOLOGIC CONSTRICTION or obstruction of its BLOOD VESSELS, or an absence of BLOOD CIRCULATION. "It has been reported that STC2 expression is induced by oxidative stress and hypoxia, and STC2 overexpression contributes to antiapoptotic activity and survival of ischemia nerve cells." (PMID 24606961, 2014).
laryngeal squamous cell carcinoma (2 papers, 2014 to 2021). A squamous cell carcinoma that arises from the larynx. "The roles of STC1 and STC2 in laryngeal squamous cell carcinoma (LSCC) remain unknown." (PMID 24743310, 2014).
lung adenocarcinoma (2 papers, 2020 to 2022). A carcinoma that arises from the lung and is characterized by the presence of malignant glandular epithelial cells. "In human lung adenocarcinomas, STC1 gene expression is well correlated with STC2, suggesting that STC1/2 is expressed by similar cell types." (PMID 32579928, 2020).
melanoma (2 papers, 2022). A malignant, usually aggressive tumor composed of atypical, neoplastic melanocytes. "First, high level and activity of AhR mediates the invasive/dedifferentiated phenotype of melanoma through the direct regulation of the expression of many genes involved in invasion (COL1A1, COL6A1, COL6A2, CYR61, STC2...) and dedifferentiation phenotypes (CCL2, NTM, NUAK2, SOX9, ABCG2...)." (PMID 36305167, 2022).
pancreatitis (2 papers, 2011 to 2022). Inflammation of the pancreas. "In transgenic mice, STC2 protects cells from necrosis and apoptosis in a pancreatitis model-induced by cerulein." (PMID 35501821, 2022). "Increased Stc2 expression was confirmed by Northern blot analysis four hours after induction of pancreatitis (saline WT vs. CIP WT)." (PMID 21545732, 2011). "Our mRNA analysis revealed murine pancreatic expression of Stc2 only after induction of pancreatitis by supramaximal secretagogue stimulation." (PMID 21545732, 2011). "Since PERK signalling has both physiological and pathological roles in the pancreas, STC2 expression was assessed in mouse pancreata before and after induction of injury using a cerulein-induced pancreatitis (CIP) model." (PMID 21545732, 2011). "Transgenic over-expression of STC2 in mice (STC2Tg) resulted in altered PERK signalling and decreased signs of acinar cell damage associated with cerulein-induced pancreatitis (CIP)." (PMID 21545732, 2011). "In addition, STC2 compromises calcineurin expression and calcineurin-dependent PERK phosphorylation in cerulein-induced pancreatitis mouse model." (PMID 35501821, 2022).
paraganglioma (2 papers, 2022 to 2025). A benign or malignant neoplasm arising from paraganglia located along the sympathetic or parasympathetic nerves. "STC2 positively correlates with immune scores in BLCA, KICH, KIRC, MESO, pheochromocytoma and paraganglioma (PCPG), PRAD and UVM; but negatively correlates with immune scores in BRCA, CESC, LGG, LUAD, LUSC, TGCT, THCA and UCEC." (PMID 40535801, 2025).
retinal degeneration (2 papers, 2022 to 2023). Degeneration of the retina. "Our results showed that Stc1 and Stc2 were highly expressed in the retina of wild type mice and their expression was largely unaffected by the loss of photoreceptors during retinal degeneration." (PMID 35812222, 2022). "Hence, it would be interesting to investigate how Stc1–/– and Stc2–/– mice respond when subjected to hypoxic stress or to photoreceptor loss in models of retinal degeneration." (PMID 35812222, 2022). "To investigate whether expression of Stc1 and Stc2 is affected by retinal degeneration, we analyzed their mRNA levels in rd10 mice that are characterized by a progressive loss of rod photoreceptors starting around PND15 and a loss of almost all photoreceptors at 6 months of age." (PMID 35812222, 2022). "We suggest that miR-184 targets STC2 to suppress import cellular processes of CEC, such as choroidal neovascularization, hyperpermeability, and retinal degeneration." (PMID 37507708, 2023).
sarcopenia (2 papers, 2023 to 2025). Progressive decline in muscle mass due to aging which results in decreased functional capacity of muscles. "These two genes, CPNE1 and STC2, encode proteins that have not yet been formally associated with COPD sarcopenia (i.e., Copine 1, a soluble calcium-dependent membrane-binding protein, and Stanniocalcin 2, a homodimeric glycoprotein hormone involved in the regulation of IGF1)." (PMID 37047427, 2023). "Five key CGs—NOX4, STC2, NEK6, IGSF10, and EMX2—were identified as molecular links between SSc and sarcopenia." (PMID 40977679, 2025).
acute coronary syndrome (1 paper, 2018). Signs and symptoms related to acute ischemia of the myocardium secondary to coronary artery disease. "Due to the recent discovery of Stanniocalcin-2 as a novel proteinase inhibitor of PAPP-A, we considered that it could also reflect PAPP-A enzymatic activity, with potential prognostic implications in the setting of acute coronary syndrome similarly to IGFBP-4." (PMID 29712555, 2018).
adrenocortical carcinoma (1 paper, 2022). "In another five types of adrenocortical carcinoma (ACC), BRCA, HNSC, LUSC, and TGCT, STC2 expression was related to MSI." (PMID 35937984, 2022).
angina (1 paper, 2021). "STC1 was found to be differentially expressed in culprit coronary plaques of patients with AMI versus those with stable angina, and STC2 was shown to be an independent predictor of all-cause death and readmission due to heart failure in ST-segment elevation myocardial infarction." (PMID 34685725, 2021).
Anorexia (1 paper, 2017). Lack of desire to eat (loss of appetite). "Our present study demonstrated that STC2 might be a potential target for improving anorexia and weight loss in cancer patients." (PMID 29207625, 2017). "Similarly, STC2 treatment also induced anorexia in hyperphagic leptin-deficient mice, leading to a significant reduction in body weight and improvement of blood glucose levels." (PMID 29207625, 2017). "Together, these results clearly indicate that STC2 could also lead to anorexia and body weight loss in ob/ob mice." (PMID 29207625, 2017). "To further explore whether STC2 mediated anorexia and weight loss was dependent on hypothalamic effect, we administrated recombinant STC2 protein or vehicle control (PBS) into the lateral ventricle of C57BL/6 mice, and monitored their food intake over time." (PMID 29207625, 2017). "Finally, we analyzed potential mechanisms of STC2-induced anorexia effects in mice." (PMID 29207625, 2017). "Therefore, we speculate that tumor-derived STC2 might be involved in cancer-induced anorexia, which needs to be determined in the future studies." (PMID 29207625, 2017).
astrocytoma (1 paper, 2022). "In the first panel, i.e., GL208, the expression of STC2 was found to be highly elevated in GBM tissues compared to normal tissues or astrocytoma tissues." (PMID 35790735, 2022).
bone osteosarcoma (1 paper, 2023). A usually aggressive malignant bone-forming mesenchymal neoplasm arising from the bone. "Above results shall provide promising directions for further exploring the mechanism of STC2 regulation on bone osteosarcoma development." (PMID 36803385, 2023).
brain cancer (1 paper, 2022). A primary or metastatic malignant neoplasm affecting the brain. "To explore the association between the expression of STC2 and the grades of brain cancer, we performed a brain cancer tissue microarray analysis using two different panels." (PMID 35790735, 2022).
chronic thromboembolic pulmonary hypertension (1 paper, 2025). Chronic thromboembolic pulmonary hypertension (CTEPH) is characterized by the persistence of thromboemboli in the form of organized tissue obstructing the pulmonary arteries. "On the other hand, STC2 was reported to be involved in chronic thromboembolic pulmonary hypertension downstream of TGF-induced protein." (PMID 41155293, 2025).
Cirrhosis (1 paper, 2019). A chronic disorder of the liver in which liver tissue becomes scarred and is partially replaced by regenerative nodules and fibrotic tissue resulting in loss of liver function. "Single factor analysis showed both STC2 mRNA and protein have nothing to do with sex, age, number of tumor, whether combined with cirrhosis (all P>0.05), but related to tumor diameter, stage, tumor metastasis, carcinoma emboli in the portal vein, and the degree of tumor differentiation (all P<0.05)." (PMID 30962272, 2019). "Our study found that the expression of STC2 mRNA and protein in HCC were not related to sex, age, number of tumor, whether combined with cirrhosis." (PMID 30962272, 2019).
coronary artery diseases (1 paper, 2021). "Among hypoxia-responsive genes identified in our in vitro hypoxic system, we also found potential cardiac biomarkers (BIRC5, ENG, HMOX1, VEGF, STC1, STC2, and SERPINE1) which they may have potential clinical value in the diagnosis and prognosis of coronary artery diseases." (PMID 34685725, 2021).
dyslipidemia (1 paper, 2018). "Thus, STC2 may be a promising therapeutic target for fatty liver and dyslipidemia." (PMID 30038584, 2018).
female infertility (1 paper, 2024). Diminished or absent ability of a female to achieve conception. "STC1 and STC2 contribute to the pathophysiology of several diseases, including female infertility- and pregnancy-associated conditions, and even tumorigenesis of reproductive organs." (PMID 39186548, 2024).
hemangioma (1 paper, 2023). A benign vascular lesion characterized by the formation of capillary-sized or cavernous vascular channels. "In this study, an infantile primary hemangioma endothelial cells (HemEC) were used to explore the potential function of STC2 in HA." (PMID 37492297, 2023). "Stanniocalcin-2 (STC2), a secreted glycoprotein that is involved in the regulation of angiogenesis, was proposed as one of the mechanisms of neovascularization in hemangioma (HA)." (PMID 37492297, 2023).
hypophosphatemia (1 paper, 2020). Lower than normal levels of phosphates in the circulating blood. "Additionally, Stc2 expression was downregulated in mice with hypophosphatemia (PhexHyp), whereas mice on high-phosphate diet resulted in increased kidney Stc2 mRNA expression." (PMID 32296395, 2020).
keloid (1 paper, 2022). An irregularly shaped, elevated mark on the skin caused by deposits of excessive amounts of collagen during wound healing. "Compared to normal group, the relative expression levels of SDC4, NOX4, DAMM1, and STC2 in keloid fibroblasts were 0.28 ± 0.13, 2.07 ± 0.32, 2.11 ± 0.63, and 1.87 ± 1.56, respectively." (PMID 35719372, 2022). "In addition, we also conducting a qRT-PCR experiment for detecting differential expression of SDC4, NOX4, DAMM1, and STC2 between keloid and normal tissue." (PMID 35719372, 2022). "In this present study, innovatively combining SVM-RFE and LASSO-logistic regression methods, we identified four biomarkers (STC2, SDC4, DAAM1, and NOX4) for keloid and further explored the role of ICI on keloid." (PMID 35719372, 2022).
nonalcoholic fatty liver disease (1 paper, 2017). "Moreover, STF remarkably downregulated expression of STC2 gene involved in endoplasmic reticulum-stress through PERK pathway in nonalcoholic fatty liver disease." (PMID 28068976, 2017).